CEMIP (cell migration inducing hyaluronidase 1)
Diseases named in the same sentence as CEMIP in open-access papers (continued):
Sharing a sentence is not in itself a finding about the gene and the disease.
tumor (85 papers, 2010 to 2025). "CEMIP is a metastasis-related gene that is associated with tumor invasion, cell death, and metabolism reprogramming; however, its putative ability as a prediagnostic genetic marker was not discussed before." (PMID 38698020, 2024). "The loss of exosomal CEMIP diminishes tumor cells and vasculature interaction, thus impeding their invasive capacity in the brain." (PMID 37958619, 2023). "In representative cases of metastatic HCC samples, immunohistochemistry results also corroborate the role of CEMIP in mediating tumor-associated neovascularization." (PMID 36639658, 2023). "In gain- and loss-of-function experiments, the overexpression of CEMIP is accompanied by increased proliferation and migration of tumor cells, and CEMIP deficiency is associated with decreased in tumor cell proliferation and migration." (PMID 37662915, 2023). "The GSEA results also revealed the activation of tumor hallmarks associated with high CEMIP expression levels, i.e., angiogenesis, EMT, and TGF-beta overexpression." (PMID 36639658, 2023). "The expression of CEMIP has previously been associated with tumor progression and fibrotic diseases, our study reveals a previously unrecognized role of CEMIP-mediated ECM stiffness in lung metastasis in HCC." (PMID 36639658, 2023). "High CEMIP levels are secreted by benign colorectal adenomas and remain high in different CRC tumor stages, suggesting that CEMIP has potential as an early diagnostic marker." (PMID 36291875, 2022). "Using clinical BC specimens, we found CEMIP expression was associated with a larger tumor size, distant metastasis, and even death." (PMID 35370456, 2022). "For example, the expression of CEMIP has been implicated in promoting tumor cell proliferation and survival." (PMID 36291875, 2022). "We show for the first time REST directly regulates CEMIP and loss of REST contributes to HA depolymerization and tumor progression by upregulating CEMIP." (PMID 35177031, 2022). "CEMIP plays an important role in guiding the penetration of tumor-associated macrophages." (PMID 37662915, 2023). "Consistently, CEMIP has been implicated in various fundamental aspects of tumor biology." (PMID 36291875, 2022). "By upregulating the pro-inflammatory cytokines encoded by Tnf, Ptgs2 and Ccl/Cxcl, the uptake of CEMIP-positive exosomes by brain endothelial cells and microglia can induce differentiation and inflammation of perivascular endothelial cells, thereby promoting vascular remodeling and tumor metastasis." (PMID 33828985, 2021). "Tumor-derived exosomes usually contain a cell migration-inducing and hyaluronan-binding protein (CEMIP) that can induce pro-inflammatory changes in microglia (M1), later leading to tumor progression in the brain microenvironment." (PMID 40761875, 2025). "In mucosal EVs from normal tissue and colon tumors analyzed by LC-MS/MS, CEMIP was specifically found in tumor-derived EVs." (PMID 39851567, 2025). "Cerebral metastatic cells utilize CEMIP (cell migration-inducing and hyaluronan-binding protein)-enriched EVs to promote tumor-endothelial adhesion." (PMID 40564894, 2025). "While investigating the tumor biological functions of CEMIP, attention has shifted toward understanding the regulation of CEMIP expression itself." (PMID 38390387, 2024). "MMP13, CEMIP, and DESC1 encode proteins important for degradation of extracellular matrixes, expressed in the tumor invasion front, and are reported to increase cell migration and tumor cell extravasation." (PMID 39468006, 2024). "Previous studies have claimed that CEMIP acts as a stimulator in tumor cell growth, invasion, and spread of the tumors." (PMID 39481283, 2024). "Consistent with these activities of HA digestion products that can be generated by hyaluronidases, the knockdown of CEMIP expression in tumor cells greatly reduces their ability to metastasize to the brain but not other organs." (PMID 39454959, 2024).
tumor (continued). "CEMIP, documented across various tumor types, correlates with enhanced cellular motility, invasiveness, and fortified resistance against pharmacological interventions." (PMID 39624211, 2024). "Among these genes, six genes are potential regulator of tumor metastasis, including CEMIP, FBN2, TIAM1, ITGA2, ARHGAP42, and GPRIN3." (PMID 38971758, 2024). "Expression of HCP5 acted as a sponge for miR-4656, preventing miR-4656 from suppressing the cell migration-inducing hyaluronidase 1 (CEMIP) gene, leading to upregulated expression of CEMIP, which plays a key role in tumour proliferation." (PMID 38052806, 2023). "CEMIP regulates the growth of tumor cells by regulating downstream molecular BiP to reduce cell apoptosis, activate autophagy, enhance glucose uptake, and survive in the harsh environment of hypoxia." (PMID 37662915, 2023). "Research on CEMIP in non-neoplastic diseases is increasing, including infection, fibrosis, and activation of immune cells, especially in inflammatory osteoarthritis (OA)." (PMID 37662915, 2023). "Exosomes derived from brain metastatic breast cancer cells contain cell migration-inducing hyaluronan binding protein (CEMIP), which increases vascular co-option and elevates the brain metastatic potential of tumor cells in vitro." (PMID 37958619, 2023). "Accumulating evidence showed that CEMIP was potential to serve as a therapeutic target for tumor metastasis." (PMID 36849460, 2023). "Collectively, we proved that pirfenidone blocks TGF-β1-induced fibrotic changes via the inhibition of the canonical Smad2/3 signaling pathway as well as the reduction in CEMIP expression levels, thus ameliorating the tumor mechano-environment." (PMID 36639658, 2023). "After being combined with these miRNAs, the expression level of CEMIP is downregulated that affects the progression of tumor cells." (PMID 37662915, 2023). "Previous studies have demonstrated that CEMIP overexpression promotes tumor cell proliferation and metastasis, leading to enhanced tumor malignancy." (PMID 37668818, 2023). "Studies have demonstrated that targeted delivery of shCEMIP prevents CEMIP expression and is crucial for preventing tumor cell proliferation and migration." (PMID 37662915, 2023). "Abnormal expression of CEMIP can also regulate non-neoplastic diseases, such as inflammation and infection." (PMID 37662915, 2023). "CEMIP immunoreactivity was mainly observed in tumor cells, alveolar type II cells, and some fibroblasts around the tumor." (PMID 36639658, 2023). "The results demonstrated that more tumor cells adhered to LFs with CEMIP overexpression compared to their counterpart." (PMID 36639658, 2023). "Together, these findings demonstrate CEMIP-mediated Matrix Stiffening can increase metastasis and promote aberrant tumor vasculature during HCC progression." (PMID 36639658, 2023). "In previous chapters, we have outlined the existing information on the role of CEMIP in tumor cell proliferation and metastasis." (PMID 37662915, 2023). "It has been reported that CEMIP not only acts on tumor cells to enhance their proliferation and metastasis ability but also contributes to cell survival and growth by modifying the structure or composition of the cell microenvironment." (PMID 37662915, 2023). "In view of the numerous and meaningful physiological and pathological functions shown by CEMIP, it is promising to design drugs targeting CEMIP to alleviate OA, anti-infection, delay skin aging, and combat tumor proliferation and migration." (PMID 37662915, 2023). "Although there has been extensive research on the relationship between the overexpression of CEMIP and tumor malignancy, reports on the use of natural active compounds to inhibit its expression are currently limited." (PMID 37668818, 2023).
tumor (continued). "Given the significant role that CEMIP plays in tumor malignancy, it has attracted considerable attention as a promising target for tumor therapy." (PMID 37668818, 2023). "Taken together, these findings indicated that CEMIP improved the tumor permissive abilities of LFs, in terms of tumor cell adhesion and colony formation." (PMID 36639658, 2023). "We further analyzed the expression of CEMIP in tumor tissue with IHC assay and found that the expression of CEMIP in the COS-treated group was significantly lower than in the control group." (PMID 37668818, 2023). "The tumor colony area was significantly larger in the CEMIP-overexpressing group than in the control group." (PMID 36639658, 2023). "Although numerous mechanisms have been suggested, the way in which CEMIP contributes at the molecular level to tumor progression and metastasis is still poorly understood." (PMID 36291875, 2022). "Some studies have indicated that CEMIP expression is further increased in metastatic lesions of CRC compared with the primary tumor." (PMID 36291875, 2022). "In a landmark paper, Lyden and colleagues have recently demonstrated that tumor-derived exosomal CEMIP can contribute to the formation of a pre-metastatic niche and metastasis formation in the brain." (PMID 36291875, 2022). "As an oncogene, CEMIP does more than merely enhance cell proliferation and metastasis, it also plays a vital role in the drug resistance of tumor cells." (PMID 35957875, 2022). "The results reveal that cell migration-inducing protein (CEMIP), also known as KIAA1199, is significantly overexpressed in PCa-AR cells, promoting tumor metastasis via metabolic reprogramming." (PMID 35013120, 2022). "The tumor-infiltrating lymphocytes most closely related with CEMIP expression in BC were CCL7, CCL14, CCL20, and CXCL14." (PMID 35370456, 2022). "CEMIP has been reported to play a crucial role in the regulation of several signaling pathways, mainly in the context of tumor cells." (PMID 36291875, 2022). "Consistently, treatment with GSK-J4, an inhibitor of the demethylase, downregulates CEMIP expression and concomitantly decreases tumor growth and migration." (PMID 36291875, 2022). "Elevated CEMIP is evident in malignancies, while CEMIP suppression impairs tumor growth, epithelial-mesenchymal transition, and metastasis." (PMID 35013120, 2022). "Decreasing BiP in cells via regulating CEMIP expression makes the cells sensitive to hypoxia therapy, reduces glucose uptake, and leads to tumor regression in vivo." (PMID 36451490, 2022). "In contrast with the ambivalent role of the traditional HYAL members, the more recently characterized HA-degrading TMEM2 and CEMIP appear to be involved in tumor progression in a more straightforward manner." (PMID 33809973, 2021). "CEMIP is induced in colon cancer cells and its overexpression correlates with poor survival and its knockout leads to tumor growth attenuation and increased HA deposition." (PMID 33809973, 2021). "CEMIP encodes the cell migration-inducing and hyaluronan-binding protein, which regulates epithelial-mesenchymal transition (EMT), tumor cell growth and migration." (PMID 34804124, 2021). "The results presented in this study provide strong evidence that CEMIP upregulates BiP at the transcriptional level to mediate resistance to tumor microenvironments often characterized by oxygen and nutrient depletion." (PMID 31303964, 2019). "Their study revealed that CACS19 reversed the tumor-suppressive effect of miR-140-5p by competing for the MREs with CEMIP mRNA, miR-140-5p’s direct target, which led to an upregulation of CEMIP mRNA." (PMID 31744051, 2019). "Activation of autophagy is one way in which CEMIP-mediated BiP upregulation can protect cells from apoptosis in hypoxia and contribute to tumor growth." (PMID 31303964, 2019). "Univariate analysis revealed significant prognostic factors including high CEMIP expression, age, anticancer treatment, and tumor stage (P < 0.05)." (PMID 29467409, 2018).
tumor (continued). "Tumors that did grow had increased deposition of hyaluronan, linking CEMIP participation in hyaluronan degradation to the modulation of tumor phenotype." (PMID 26437221, 2015). "Since solid tumors are often accompanied by hypoxia, we next explored if tumor cells with upregulated CEMIP are located in a hypoxic environment." (PMID 26009875, 2015). "Importantly, our data indicate that bexarotene reduces LMWHA and HMWHA accumulation by suppressing the expression of HAS1, HAS3, and CEMIP in tumor cells and HAS1 and HAS2 in fibroblasts." (PMID 39858106, 2025). "Proteomic analysis confirmed the presence of CEMIP in the tumor-generated EVs." (PMID 39851567, 2025). "Both endothelial and glial cells internalized EVs with CEMIP, and this induced the branching of endothelial cells in the perivascular space via proinflammatory cytokines, thereby promoting colonization by brain-metastasizing tumor cells." (PMID 39851567, 2025). "Genetic ablation of CEMIP significantly impairs tumor-vascular co-option capacity." (PMID 40564894, 2025). "Furthermore, CEMIP expression in tumor exosomes increases metastases to the brain in mice, and increased CEMIP expression in human tumors is associated with increased numbers of brain metastases in patients." (PMID 39454959, 2024). "Moreover, ChIP analysis of tumor tissues revealed that the recruitment of BACH1 to the promoters of CEMIP, CXCL14, and NGFR was markedly enhanced in tumors from the Keto diet group compared to the Ctrl group." (PMID 38838145, 2024). "Targeting CEMIP may amplify the efficacy of ICB by boosting tumor immunogenicity and augmenting T cell activation and infiltration." (PMID 38390387, 2024). "It has been demonstrated that CEMIP regulates cell proliferation, differentiation, migration, and invasion, promoting tumor growth through activation of pathways including Notch signaling pathway, the Wnt signaling pathway, and integrin-mediated AKT and ERK-MAPK intracellular signaling." (PMID 38835051, 2024). "Considering we had proved that CEMIP activated CDC42/MAPK pathway, and it was reported that MAPK signaling was a key regulator of epithelial-mesenchymal transition (EMT) and tumor metastasis, we deduced that CEMIP promoted CRC metastasis via MAPK signaling-induced EMT." (PMID 36849460, 2023). "First is whether CEMIP plays some important and unknown role in some pathophysiological processes of non-tumor diseases." (PMID 37662915, 2023). "Plasma CEMIP expression levels were significantly upregulated as the tumor volume increased, while pirfenidone treatment could significantly downregulate the circulating CEMIP level." (PMID 36639658, 2023). "Specifically, MMP9, MMP13, MMP11, and CEMIP were positively associated with the tumor immune microenvironment, while SLPI, SLC2A1, SERPINB5, HK2, CEACAM6, and CEACAM5 were negatively associated with the tumor immune microenvironment." (PMID 37234801, 2023). "The critical role of CEMIP in promoting tumor migration and invasion has been identified by numerous studies, but the precise molecular mechanism is still unknown." (PMID 37662915, 2023). "Altogether, our data suggest that CEMIP can activate LFs to facilitate tumor metastases." (PMID 36639658, 2023). "CEMIP has been shown to activate macrophages in the local tumor microenvironment." (PMID 37662915, 2023). "Considering the importance of intercellular communication between tumor cells and the surrounding microenvironment, we then evaluated whether CEMIP serves as a functional factor secreted by HCCs that affects the features of MRC5 human lung fibroblasts." (PMID 36639658, 2023). "Collectively, CEMIP is potential to serve as a therapeutic target for tumor metastasis." (PMID 36849460, 2023). "Moreover, immunohistochemistry also confirmed the elevated expression of CEMIP in the tumor tissues." (PMID 35543351, 2022).
tumor (continued). "Here, we review our current understanding of the mechanisms through which CEMIP contributes to tumor progression and suggest ways in which the perturbation of CEMIP expression and function might be leveraged therapeutically." (PMID 36291875, 2022). "In addition, Chen Y found that CEMIP can promote a variety of tumor processes by affecting tumor proliferation, dedifferentiation, and the tumor microenvironment." (PMID 35299749, 2022). "CEMIP expression and activity can be therapeutically targeted at a number of levels, and preliminary findings in animal models show encouraging results in terms of reduced tumor growth and metastasis, as well as combating therapy resistance." (PMID 36291875, 2022). "A number of observations support the notion that CEMIP might also contribute to a tumor- and metastasis-promoting inflammatory and immunosuppressive microenvironment." (PMID 36291875, 2022). "In different breast and gastric tumor models, CEMIP expression has been found to promote metastasis to the lung and liver, although this might be due at least in part to concurrent accelerated primary tumor growth." (PMID 36291875, 2022). "There is also increasing evidence indicating that CEMIP may be expressed in cells within the tumor microenvironment that promote tumorigenesis and metastasis formation, although this remains in an early stage of investigation." (PMID 36291875, 2022). "However, the relevance of CEMIP expression in the tumor microenvironment remains largely to be investigated." (PMID 36291875, 2022). "A number of observations suggest that CEMIP expression may contribute to the metabolic adaptation required for tumor progression and therapy resistance." (PMID 36291875, 2022). "Furthermore, through its interaction with BiP, CEMIP expression increases glucose uptake by tumor cells, which promotes their survival under hypoxic conditions." (PMID 36291875, 2022). "The hyaluronidase activity of CEMIP may account for its tumor- and metastasis-promoting role in a number of ways." (PMID 36291875, 2022). "The silencing of CEMIP in resistant tumor cells improves the therapeutic response." (PMID 36291875, 2022). "Moreover, elevated levels of CEMIP in tumor tissues and exosomes from patients with brain metastasis can predict the progression of brain metastasis and patient survival." (PMID 33828985, 2021). "Rodrigues et al63 identified the distinct increase of cell migration‐inducing and hyaluronan‐binding protein (CEMIP) expression in brain‐tropic EVs in comparison to lung‐tropic or bone‐tropic EVs and demonstrated that ablation of CEMIP in tumour cells hinders brain metastasis." (PMID 33145869, 2021). "In addition, a study also showed that tumor exosomal cell migration-inducing and hyaluronan-binding protein (CEMIP) can promote BM, highlighting the complexity of cross-talk between different molecules." (PMID 33498505, 2021). "CEMIP promotes tumor cell survival through the breakdown of glycogen." (PMID 31744051, 2019). "A significant increase in CEMIP expression at both the mRNA and protein levels was observed in both these cell lines after a shorter exposure time to hypoxia, suggesting that upregulated CEMIP in tumor cell lines is a general consequence of hypoxic stress and not tissue specific." (PMID 26009875, 2015). "Thus, the contribution of CEMIP to tumor phenotype appears to generally be mediated by the native protein." (PMID 26437221, 2015). "Within the primary tumor specimens, adjacent normal tissues, as well as most adenocarcinoma cells in the mucosa, were negligibly stained by the anti-CEMIP antibody." (PMID 26009875, 2015). "Facilitation of tumor growth by CEMIP overexpression may be due, in part, by protecting cells from apoptosis; as deletion of CEMIP resulted in increased cleaved caspase-3 staining in CEMIP knockout DLD-1 xenografts with significantly attenuated growth." (PMID 26437221, 2015).